IL6 (interleukin 6)
Diseases named in the same sentence as IL6 in open-access papers (continued):
Sharing a sentence is not in itself a finding about the gene and the disease.
chronic hepatitis C (26 papers, 2012 to 2025). "With this overview, the present study was planned to identify the relationship between IL-6 and iron regulation in chronic hepatitis C seropositive Egyptian patients on regular HD." (PMID 32720970, 2020). "This study investigated the role of IL-6 and IL-28B gene polymorphisms on SVR in IVDU patients diagnosed with chronic hepatitis C infection." (PMID 27812403, 2016). "A retrospective cohort study showed that elevated serum IL-6 levels were associated with higher incidence rates of hepatocellular carcinoma in female patients with chronic hepatitis C but not in male patients." (PMID 37370004, 2023). "Additionally, a significant negative correlation has also been observed between the serum levels of vitamin D either with serum IL-6 or with the degree of liver damage in patients with chronic hepatitis C." (PMID 27681697, 2016). "The putative low producing IL-6 phenotype may play a protective role against chronic hepatitis C infection by helping to clear the viral particles during standard therapy." (PMID 27812403, 2016). "Unexpectedly, in a multivariate analysis higher serum IL-6 level was an independent risk factor for HCC development in female but not in male chronic hepatitis C patients." (PMID 22470194, 2012). "In contrast, the wild-type genotype for the IL6-174G/C polymorphism was linked to high IL-6 levels and HCV viral load, suggesting that this genotype may be a contributing factor to the development of chronic hepatitis C in patients from the Amazon region." (PMID 35336914, 2022). "Chronic hepatitis C patients with rs1800795-IL6 CC genotype and lower IL-6 serum level may have an attenuated adoptive immune response, directed away from damaging, pro-inflammatory and autoimmune to predominately suppressive and anti-viral inflammatory response." (PMID 27812403, 2016). "In another study, chronic hepatitis C patients presented elevated serum levels of IL-10, IFN-γ, IL-6, and IL-4, while IL-1, IL-2, IL17, IL-22, IL-13 TNF, IL-12p70, and IL-15 levels were lower in patients compared to healthy controls." (PMID 29977152, 2018). "Levels of inflammatory markers like IL-6, TNF-α and CRP are elevated in patients with chronic hepatitis C." (PMID 25438910, 2014). "This is an important finding since some studies have shown that the largest proportion of cellular infiltrate found in a liver with chronic hepatitis C is TH1 cells, such as IL-1b, IL-2, IL-6, IL-8, TNF-α and IFN." (PMID 22830036, 2012). "δ-Tocotrienol also inhibits expression of IL-6 and TNFR induction in chronic hepatitis C patients." (PMID 30031388, 2018). "Confirming our results, IL-6 serum levels were not altered after DAA treatment in another Brazilian cohort with chronic hepatitis C patients." (PMID 29977152, 2018). "Among 60 chronic hemodialysis patients with and without chronic hepatitis C virus infection, serum prohepcidin levels were significantly correlated with serum IL-6 levels." (PMID 24576354, 2014). "Indeed, accumulating evidence showed an increase in proinflammatory mediators, principally IL-6, IL-1β, interferon-γ (IFN-γ), and TNF-α in depressed individuals and in patients developing depressive symptoms after therapeutic treatments, such as IFN-α therapy for chronic hepatitis C." (PMID 35886944, 2022).
Disseminated intravascular coagulation (26 papers, 2013 to 2025). Disseminated intravascular coagulation is characterized by the widespread activation of coagulation, which results in the intravascular formation of fibrin and ultimately thrombotic occlusion of small and midsize vessels. "The mechanism of action of TCZ depends on its inhibitory effect of IL-6R, therefore decreasing IL-6 mediated increased vascular permeability, immune cells activation, histamine release from mast cells, activation of coagulation, and development of disseminated intravascular coagulation (DIC)." (PMID 35203844, 2022). "Previous studies report an elevated IL-6/IL-10 ratio in septic infants, and specifically in those with disseminated intravascular coagulation, which is often associated with fungal and Gram-negative bacterial infections that are known to elicit different cytokine responses." (PMID 32407417, 2020). "Via trans-signaling, IL-6 leads to characteristic manifestations of severe CRS, e.g. vascular leakage, activation of complement and coagulation cascade inducing disseminated intravascular coagulation." (PMID 35154124, 2022). "The serum levels of IL-6, TNF-α and serum CCHFV titer at admission were significantly and positively correlated with disseminated intravascular coagulation (DIC) scores (r = 0.626, p = 0.0002; r = 0.461, p = 0.009; and r = 0.625, p = 0.003, respectively)." (PMID 25066751, 2014). "Moreover, IL-6 contributes to the hypercoagulability status together with TNF-α and IL-1, a phenomenon which, if accompanied by severe inflammatory syndrome, leads to disseminated intravascular coagulation." (PMID 37834356, 2023). "Biopsies obtained at the end of the study period did not demonstrate evidence of hyperacute rejection, disseminated intravascular coagulation (DIC), hyperinflammation, excessive cytokine release (IL-2, IL-6, IL-10, IL-13), or complement dysregulation." (PMID 38020483, 2023). "The ARDS group also had higher levels of IL-6, IL-8, and IL-10 than the non-ARDS group, and the levels of these cytokines correlated significantly with coagulation parameters and disseminated intravascular coagulation (DIC)." (PMID 34088317, 2021).
H1N1 virus infection (26 papers, 2009 to 2025). "The TNF gene was associated with disease severity, whereas IL1B and IL6 SNPs were associated with influenza A (H1N1) virus infection." (PMID 26657940, 2015). "Another study in critically ill patients with ARDS caused by 2009 H1N1 virus infection has shown that the hallmarks of disease severity were elevated levels of IL-6, IL-15, IL-8 and TNF-α." (PMID 22235288, 2012). "In H1N1 influenza, increase in IL-6 is associated with decreases in positive affect." (PMID 28278190, 2017). "Our results also corroborate with previous studies showing an IL-6 increase with respiratory severity in H1N1 influenza." (PMID 24885241, 2014). "Significantly higher levels of IL-1β and IL-6 were detected in all patients with H1N1 virus infection compared to controls." (PMID 23737648, 2013). "In conclusion, H1N1 virus infection induces an early and significant upregulation of both interleukins IL1β and IL-6 plasma expressions." (PMID 23737648, 2013). "It has proved that high levels of IL-6 were able to mediate acute lung injury, and had a negative correlation with the PaO2∶FiO2 ratio in severely affected patients with 2009 H1N1 virus infection." (PMID 22235288, 2012). "With disease progression, higher levels of sera IL-6 and IL-10 were found in severe pandemic H1N1 influenza patients." (PMID 22174866, 2011). "In our critically ill patients with nvA(H1N1) virus infection we found increased levels of some cytokines: IP-10, TNFα, IL-15, IL-12, IL-6, IL-8 and IL-9." (PMID 21062445, 2010). "In our critically ill patients with novel influenza A(H1N1) virus infection, the hallmarks of the severity of disease were IL-6, IL-15, IL-8 and TNFα." (PMID 21062445, 2010). "In particular, IL-1β and IL-6 have been identified as markers of severity in acute lung injury during influenza A (H1N1) virus infection; IL-1β in particular has been proposed as a good early marker of the severity and progression of lung inflammation in mechanically ventilated patients." (PMID 26657940, 2015). "For instance, significantly higher levels of IL-6 were detected in children with H1N1 virus infection, and the upregulation of IL-6 likely plays a proinflammatory role in H1N1 virus infection, which might be the crucial factor for airway inflammation and bronchial hyperreactivity in these children." (PMID 37577373, 2023). "More in particular, IL-6 up-regulation was significantly correlated with the severity of respiratory compromise, testified by a lower SpO2 at admission and higher fever observed in this subset of children, as previously reported in patients with H1N1 virus infection." (PMID 23737648, 2013). "Therefore, this study suggests that the protective effect of hUCMSC-EVs against lung damage caused by influenza A virus (H1N1) infection may be related to the reduction in inflammatory cytokine levels of TNF-α, IL-1β, and IL-6, thereby alleviating pulmonary inflammation." (PMID 41009408, 2025). "Pyrogallol treatment reduced the increased levels of proinflammatory mediators (IL‐6, IL‐8, IP‐10, MCP‐1, RANTES, and TNF‐α) induced by H1N1 virus infection." (PMID 38617435, 2024). "Meanwhile, our results showed that the increased production of pro-inflammatory mediators (IL-6 and TNF-α) triggered by H1N1 virus infection was significantly decreased in A549 cells with h-PGDS overexpression." (PMID 37891648, 2023). "It has been reported that pregnant women infected with H1N1 influenza had significantly higher serum levels of IL‐6, IL‐10 and TNF‐α than healthy pregnant women, and IL‐6 was correlated with the severity of the disease." (PMID 37638092, 2023). "In mouse model of H1N1 influenza, peramivir inhibits the levels of TNF-α, IL6 and IFN-γ in the lung tissue." (PMID 35296098, 2022). "CS exposure and H1N1 virus infection can activate NF-κB signaling pathway and NLRP3 inflammasome and promote proinflammatory cytokine (IL-6, IL-1β) release and Th17 cell differentiation." (PMID 34393799, 2021).
H1N1 virus infection (continued). "The H7N9, H7N7 and H5N1 infected mouse lung transcriptome also showed higher levels of CXCL13, IL-6, IFNG, IFNB1, IRF9, IRF1, and TNF compared with 2009 pandemic H1N1 virus infections." (PMID 28558796, 2017). "In particular, IL-6 and TNF-α are the primary contributors to hypercytokinemia and were significantly increased following 2009 H1N1 virus infection." (PMID 22952892, 2012). "The overproduction of IL-6 is an important risk factor for worse outcomes in H1N1 influenza, SARS,156 MERS,157 and SARS-CoV-2.158, 159 Tocilizumab-dependent neutralization of IL-6 as a SARS-CoV-2 therapeutic is not fully elucidated." (PMID 33958704, 2021). "The clinical respiratory signs and lung pathology in swine influenza-infected pigs are commonly induced by the pro-inflammatory cytokines such as IFN-α, TNF-α, IL-1 α and β, and IL-6 in bronchoalveolar lavage fluids and the amount of viral load in the lung tissue." (PMID 19317918, 2009). "Severe PR8 (H1N1) virus infection induced viral dose dependent elevation of IL-6 and KC/GRO level in early phase of infection, which corresponded to peak viral titer and the course of infection, but only IL-6 level showed significant reduction after prophylactic oseltamivir treatment." (PMID 27110056, 2016).
hepatitis B (26 papers, 2011 to 2025). "Our findings propose on one side, a positive association between TLR2 polymorphisms and hepatitis B activity, and, on the other, the valuable role of IL-6 a good marker of disease progression in chronic HBV-infected patients." (PMID 35119591, 2023). "It has also been shown that miR-125b is associated with hepatitis B and has been targeted with genes that include IL6, DDX3X, STAT2, STAT3, SMAD4, CDKN1B, MAP3K1 and so on from our results." (PMID 34988221, 2021). "The effect of inhibition of IL-6 signalling on the course of viral hepatitis remains to be elucidated, since IL-6 has been implicated in both hepatitis B related hepatocellular injury, as well as in hepatitis B viral clearance." (PMID 22081766, 2011). "Abnormal expression of TNF-α, CRP and IL-6 inflammatory markers can promote liver inflammation, fibrosis and damage and aggravate liver function damage and disease severity of hepatitis B complicated with alcoholic cirrhosis." (PMID 41281287, 2025). "As a common pro-inflammatory factor, the increased level of IL-6 has been reported in various infections and tumors, and there have also been studies on the antiviral mechanism of IL-6 in hepatitis B." (PMID 34782855, 2021). "The role of IL-6 in the development of hepatitis B flare was investigated previously." (PMID 35163330, 2022). "In addition, J774A.1 macrophages treated by the codelivery system were successfully differentiated into the M1 phenotype and expressed enhanced cytokines with anti-hepatitis B effects such as interleukin 6 (IL-6) and tumor necrosis factor-α (TNF-α)." (PMID 35890334, 2022). "Hepatitis B virus infection induces inflammatory cytokine secretion (e.g., TNF-α, IL-1β, IL-6), which promotes bone resorption and reduces bone formation by activating osteoclasts and inhibiting osteoblast function." (PMID 41404370, 2025). "The core of subnetwork 2 is ESR1, CASP3, and IL6, which are closely related to the TNF signalling pathway and the hepatitis B pathway." (PMID 36818231, 2023). "NAFLD is linked to several pathways, including the cancer pathway, the Hepatitis B pathway, the VEGFR1 signaling pathway, the IL-6 signaling pathway, the AP1 signaling pathway, and the HIF signaling pathway." (PMID 35170400, 2022). "Furthermore, we identified that combination of baseline serum IL-6 level, serum ALT level at the peak of serum HBV DNA and HBV genotype reliably predicted the development of subsequent hepatitis B flare." (PMID 35163330, 2022). "Thus, it is suggested that the frequency of the IL6-174G/C polymorphism may not be directly related to the development of hepatitis B and C in the population of this study, which has a tri-hybrid composition (with genetic contributions from white, black, and indigenous peoples)." (PMID 35336914, 2022).
irritable bowel syndrome (26 papers, 2012 to 2025). Irritable bowel syndrome (IBS) is a chronic functional condition of the lower gastrointestinal (GI) tract characterized by abdominal pain or discomfort and disordered bowel habit (diarrhea, constipation, or fluctuation between the two). "Veillonellaceae has been associated with exacerbating inflammation (IL-13, IL-6) and higher prevalence in patients with hepatic encephalopathy and irritable bowel syndrome patients." (PMID 37763331, 2023). "lactate V9) as adjuvant therapy for irritable bowel syndrome significantly reduced serum levels of inflammatory cytokines (IL-6 and TNF-α) in patients." (PMID 40284709, 2025). "IL-6 was also shown to increase colonic motility in a rat model of irritable bowel syndrome and inhibition of IL-6 normalized stress-induced defecation." (PMID 35805922, 2022). "Conversely, CDCA previously given to patients with irritable bowel syndrome increased the presence of inflammatory markers in the terminal ileum, including IL-6 and TNF-α." (PMID 34452145, 2021). "In a randomized controlled trial on the diet of patients with irritable bowel syndrome, serum proinflammatory IL-6 and IL-8 levels, and faecal abundance of actinomycetes, bifidobacteria, and E. faecalis were significantly lower in patients on the low-FODMAP diet." (PMID 36544908, 2022). "SP stimulates the synthesis of TNF-α, IL-1β, and IL-6 in the human colonic mucosa, increases the production of IL-1β and IL-6 mRNA in human glial cells, and co-operates with mast cells in the wall of ileum and ascending colon of irritable bowel syndrome (IBS) patients." (PMID 33353157, 2020). "Moreover, higher level of IL-6 is witnessed in irritable bowel syndrome (IBS) patients but its correlation with gastrointestinal dysfunction remains unknown." (PMID 33390844, 2021). "And compared to control rats and enteric glial cells, the expression levels of GFAP, S100B, SP, CGRP, TRPV1, TNF, IL-1β, and IL-6, were significantly higher in the colonic tissues of irritable bowel syndrome (IBS) rats and lipopolysaccharide (LPS)-treated EGCs." (PMID 40225339, 2025). "Bifidobacterium longum ES1 significantly reduces serum levels of IL-6, IL-8, and TNF-α in patients with irritable bowel syndrome (IBS), while restoring intestinal permeability and barrier function." (PMID 41299994, 2025). "Veillonella levels have been found to be higher in patients with irritable bowel syndrome, and the lipopolysaccharide (LPS) produced by Veillonella could stimulate the release of TNF-α, IL-1, IL-6 and IL-10 within Toll-like receptor (TLR) pathways." (PMID 37208752, 2023). "When considered in the context of the functional bowel disorder, irritable bowel syndrome (IBS), where plasma levels of IL-6 are elevated, this may reflect an important molecular mechanism contributing to symptom flares, particularly in the diarrhea-predominant phenotype." (PMID 23162465, 2012).
metastatic cancer (26 papers, 2002 to 2025). A carcinoma which has spread from the original site of growth to another anatomic site. "A possible explanation is the upregulation of IL-6 expression and consequent upregulation of hepcidin associated with inflammatory conditions typically observed in many patients with metastatic cancer." (PMID 33868231, 2021). "Individually, inflammatory cytokines such as OSM, IL-6, and IL-1β have been shown to promote effects associated with metastatic cancer." (PMID 31007849, 2019). "Higher levels of IL-6 in the blood of patients have been associated with advanced/metastatic cancers." (PMID 28420169, 2017). "Because NF-κB activation has been involved in many types of cancer metastasis that are likely induced by its downstream pro-inflammatory cytokines such as IL6 and GM-CSF, targeting NF-κB and its associated pathways may open a possibility for therapeutic intervention of metastatic cancer." (PMID 23437168, 2013). "Previous findings showed that Parathyroid hormone-related protein (PTHrP), receptor activator of nuclear factor-κB ligand (RANKL) and interleukin (IL)-11, IL-8, IL-6, etc, produced by metastatic cancer cells, are involved in osteolytic bone metastases." (PMID 37333824, 2023). "In metastatic cancer, these pathways are activated by pro-inflammatory cytokines such as interleukin 6 (IL-6), interleukin 1 (IL-1), tumor necrosis factor alpha (TNF-α), and interferon gamma (IFN-γ)." (PMID 35994202, 2022). "Given the key role of IL-6 in MSC-associated tumor metastasis and chemoresistance, and being secreted by many types of cells, it is a very promising approach to metastatic cancer therapy by targeting IL-6 and its signaling pathways in TME." (PMID 31130595, 2019). "Detection of IL-6 is only applicable at low concentrations, 12–300 pg/mL, for practical clinical utility in metastatic cancers." (PMID 28420169, 2017). "Biological characteristics such as lactate dehydrogenase level (LDH), lymphocyte count, or Interleukin 6 level have been correlated with poor outcome in metastatic cancer." (PMID 20537187, 2010). "Advanced/metastatic cancer patients have higher levels of IL-6 in their blood." (PMID 21686188, 2011). "Increased IL-1α expression correlated with the expression of prometastatic (IL-6 and IL-8) and anti-apoptotic genes (TRAF-1 and cIAP-2) and is associated with invasive and metastatic cancer leading to poor prognosis." (PMID 21139583, 2011). "Furthermore, we showed that the combination of PS and biological covariates such as LDH, lymphocyte and platelet counts, serum albumin and IL-6 levels is an effective strategy to predict survival for patients with advanced or metastatic cancer receiving further treatment after the first-line." (PMID 21406082, 2011). "Arterial levels of IL-6 were compared in metastatic cancer patients (n=6) were compared with arterial levels in non-metastatic patients (n=15)." (PMID 12454774, 2002). "Interestingly, since IL-6 has been found to be elevated in cancer patients with distal metastases, as compared with non-metastatic patients, an increased IL-6 concentration has been proposed as a prognostic marker in some types of metastatic cancer." (PMID 29788918, 2018).